ENSG00000252218
Synonyms: LOC124900224
Gene: Small Cajal body-specific RNA gene on chromosome 6 (43,544,144 to 43,544,270, forward strand). Ensembl gene ENSG00000252218.
Gene Ontology:
Biological process: RNA processing
Cellular component: Cajal body; nucleolus